IRF1 (interferon regulatory factor 1)
Diseases named in the same sentence as IRF1 in open-access papers (continued):
Sharing a sentence is not in itself a finding about the gene and the disease.
tumor (continued). "The ability to deacetylate IRF1 was demonstrated by SIRT1, a histone deacetylase whose activity change is associated, among other things, with tumor progression." (PMID 38396830, 2024). "Much evidence has been discovered regarding IRF1’s function in regulating DNA damage-induced apoptosis and tumor cell growth arrest." (PMID 38396830, 2024). "On the other hand, its opposite property that can lead to increased tumor growth is also evident—IRF1 activity in cells can lead to inhibition of the antitumor immune response through PD-L1 upregulation." (PMID 38396830, 2024). "The complex is transferred to the nucleus, activating the interferon adjustment factor 1(IRF1), and its transcription activity eventually leads to the anti-tumor effect of the aconic-mediated anti-tumor, and the increased PD-L1 expression." (PMID 38919624, 2024). "Baseline tumor PD-L1 and IRF1 nuclear expression (both in CD3 + T cells and in CD68 + cells) were higher in responding patients." (PMID 38519913, 2024). "In particular, the “immune checkpoint” molecule PD-L1, which is responsible for tumor immune evasion, has IRF1 as a major transcriptional regulator." (PMID 38396830, 2024). "IRF-1 also functions as a pro-apoptotic tumor suppressor through the transcriptional regulation of genes involved in cell proliferation, apoptosis, and angiogenesis." (PMID 39532800, 2024). "The expression of phospho-TAK1, phospho-NF-κB p65, and IRF1 of intratumoral cDC1 were upregulated from hsBCL9z96-treated CT26 tumor-bearing mice, as well as from MC38 tumor-bearing Bcl9/Bcl9l deficiency mice." (PMID 38811552, 2024). "IRF1 was then shown to affect tumor immune infiltration, the expression of immune checkpoint molecules, and the efficacy of immune checkpoint blockade therapy." (PMID 38927914, 2024). "Subsequently, experiments validated that DNA damage not only induced MICA expression in tumor cells via IRF1, but also upregulated PROS1 levels in HCC cells, stimulating macrophages to secrete MMP9." (PMID 38254761, 2024). "The inhibition of PD-L1 and IRF1 in combination therapy was verified with multi-color immunofluorescence assay in tumor tissues." (PMID 38164171, 2024). "In the IRF1 knockdown group, IL-2 treatment simulated the effect of IRF1 and significantly inhibited the tumor growth." (PMID 38915471, 2024). "IRF1, acting as a tumor suppressor gene, enhanced the migration of CD8+ T-cells, NK cells, and NKT cells, while also stimulating IFN-γ secretion in NK and NKT cells." (PMID 38999981, 2024). "Taken together, these results suggest that macrophage polarization in the LGG TME can be driven by interferon-gamma activation of the STAT1/IRF1/IRF5 to promote tumor progression in concert with TGFB2 levels." (PMID 38539537, 2024). "On the one hand, IRF1 can influence a number of pathways that result in the suppression of tumor growth." (PMID 38396830, 2024). "Western blot analyses of the tumors showed up‐regulations of PD‐L1, STAT1, p‐STAT1, and IRF‐1 expression in a single small tumor from APG‐157 + anti‐CTLA‐4 treated group." (PMID 38686626, 2024). "Mechanistically, we uncovered that AT-101 + lenalidomide and dexamethasone (ARd) upregulated several tumor-suppressor genes in MM/WM cell lines treated with the combination; central to which was IRF1." (PMID 36672426, 2023). "Simultaneously, JAK/STAT receptors also increase PD-L1 expression on tumor cells through interferon regulatory factor 1 (IRF1) which grants resistance to tumor cells to the innate immune system of the body." (PMID 37842239, 2023).
tumor (continued). "Down-regulation of IRF1 is frequently observed in MDS and AML and increases tumor predisposition and mutation rates in mice when combined with other cancer-promoting mutations." (PMID 37889967, 2023). "The striking difference in functional output with other IRFs is that IRF1 also drives the expression of various cell cycle inhibiting factors, making it an important tumor suppressor." (PMID 37622993, 2023). "PANoptosis was implicated in CRC and that the progression of PANoptosis inhibited IRF1-regulated tumor development in a CRC mouse model." (PMID 38129399, 2023). "These novel findings demonstrate that the interaction of CHK1 and IRF1 plays a key role in regulating the tumor immune microenvironment through MICA in HCC." (PMID 36765808, 2023). "The most spliced gene was SNHG17 with >25 splice forms and tumour associated splice events of CD44, STAT1, FAS, and IRF1 further confirming the JAK-STAT pathway enrichment from GSEA." (PMID 37091785, 2023). "According to our studies, this CHK1/IRF1/MICA axis activates anti-tumor immune cells to enhance tumor disruption through the interaction of miR-195." (PMID 36765808, 2023). "Our previous studies demonstrated that IRF1 promoted cellular apoptosis and regulated the recruitment and activation of anti-tumor immune cells in murine liver cancer." (PMID 36765808, 2023). "In WT mice, the level of expression of IRF1 is lower in colons with tumor development than in non-tumor colons." (PMID 38129399, 2023). "On one hand, IRF1 drives escape from anti-tumor immune surveillance by binding directly to the promoter of PD-L1, a ligand of the programmed death-1 (PD-1) immune checkpoint, thereby promoting its expression." (PMID 37094077, 2023). "Collectively, FOXP1 as a tumor suppressor inhibited PC progression by triggering the transcriptional activity of IRF1." (PMID 36952469, 2023). "Carboplatin-treated CAFs also upregulated the chemoattractant Ccl2, which has been associated with promoting monocyte and macrophage infiltration of the tumor site, and Irf1 and IL-1ß, which enhance M1 polarization in macrophages." (PMID 37660083, 2023). "S16, B and D) and strong inflammation-related TF activation, including Irf1 and Nfkb1, akin to previously reported tumor-infiltrating CCR7+ DCs that secrete IL-12 and activate T cells to increase antitumor activity." (PMID 37075115, 2023). "The expression of programmed cell death ligand 1 (PD-L1) on the surface of tumor cells is mediated by the subsequent stimulation of the transcription factor interferon regulatory factor 1 (IRF1), which negatively regulates the effector T cell response in turn." (PMID 37033966, 2023). "Mediated by YTDHF2, METTL3/METTL14 knockdown stabilizes STAT1 and Irf1 mRNAs, and promotes IFN‐γ‐STAT1‐Irf1 signaling, which in turn sensitizes tumor cells to PD‐1 inhibition." (PMID 36810108, 2023). "Consistent with the in vitro cell experiments, we observed that PTP 9 and anti-PD-1 cotreatment induced a significant increase in tumor expression of Cxcl11, Ccl5, Stat1, Stat3, Tap1, Irf1, Casp8, and Pdl1, compared with anti-PD-1 treatment alone." (PMID 36968224, 2023). "Numerous studies have shown that IRF1, a transcription factor that mediates IFNγ signaling, promotes both PD-L1 upregulation in tumor cells and tumor progression in vivo." (PMID 37024504, 2023). "Meanwhile, a significantly higher IRF1 level was found in the HCC tumor cells with positive MICA expression than those with negative." (PMID 36765808, 2023). "IFNγ signaling strongly induces PD-L1 expression on tumor cells through IRF1-mediated transcriptional activation of the PD-L1 gene." (PMID 37024504, 2023). "In summary, our study explored the mechanisms of DDR signaling communicating with the IRF1 pathway in regulating the HCC tumor microenvironment and can potentially serve as a therapeutic strategy in treating patients with advanced HCC." (PMID 36765808, 2023).
tumor (continued). "Of note, FOXP1-bound IRF1 promoter was found by luciferase and ChIP assays, suggesting a possibly of elevating the expression level of IRF1 that inhibited tumor cell growth and invasion." (PMID 36952469, 2023). "DNA damage regulates the interaction of CHK1 and IRF1 to activate anti-tumor immunity via the IRF1-MICA pathway in HCC." (PMID 36765808, 2023). "IRF1 is a target gene downstream of the IFN-γ/JAK/STAT1 pathway, and its deficiency can reduce tumor progression." (PMID 37185662, 2023). "Interferon regulatory factor 1 (IRF-1) is a tumor suppressor gene with antiproliferative and pro-apoptotic effects on cancer cells." (PMID 37022566, 2023). "Previous findings have shown that tumor cells increase PD-L1 expression through transcription factors such as IRF1/4, c-Myc, EGR1, c-Jun, HIF-1α, NF-κB, ATF3 and STAT3." (PMID 36854755, 2023). "IRF1 has been described as a tumor suppressor in many cancer types and suppresses MYC-driven oncogenesis." (PMID 35453756, 2022). "IRF-1 genes (Interferon (I.F.N.)regulatory factor-1) are the first specified subtype of the I.R.F. family that have physiological roles in tumor prevention, immune development, and establishing host defense against pathogens." (PMID 35330456, 2022). "As previously observed in mRNA expression level, CASP4, GPX4, IL18, NLRP1, and IRF1 were upregulated in tumor samples, whereas PLCG1 was downregulated." (PMID 35000541, 2022). "New signaling pathways of IRF-1 have been found within tumor microenvironments and in metastatic sites." (PMID 35677632, 2022). "Previously, IRF1 has been implicated not only in the regulation of CD274 (PD-L1) expression, but also in playing a role in suppressing tumour proliferation and stimulating an active immune response in tumours." (PMID 36010935, 2022). "Expression levels of the tumor cell–autonomous gene IFNGR1 and downstream signaling axis and effector genes, including JAK1, JAK2, and IRF1, were all significantly lower in PRC2-loss tumors than in PRC2-wt tumors (P < 0.05)." (PMID 35852856, 2022). "It was reported that IRF1 has physiological roles in tumor prevention, cytokine signaling, and cell growth regulation." (PMID 36110293, 2022). "SOX10 directly induces the transcription of IRF4, a negative regulator of IRF1; thus, its inhibition can enhance tumor responsiveness to anti-PD1 therapy, as observed in mice subcutaneously implanted with murine D4M melanoma cells." (PMID 36551603, 2022). "First, IRF1 is reported as an important transcription factor to regulate tumour cell PD‐L1 expression by binding to CD274 promoter." (PMID 35083874, 2022). "We also noted indications of an inflammatory response and TGF signaling in tumor-draining LN fLECs, including an upregulation of Nfkb1 expression and an enrichment of IRF1- and SMAD2-binding motifs." (PMID 35892863, 2022). "To investigate potential mechanisms of how the modulation of oncogenic EGFR signalling in tumour cells facilitates changes in the immune response, we next examined the expression of the transcription factor, IRF1, a known tumour suppressor gene." (PMID 36010935, 2022). "XAF1 forms a feedback loop with interferon regulatory factor-1 (IRF-1) and evokes its tumor suppression effect in a highly IRF-1-dependent fashion." (PMID 35902580, 2022). "Patients with higher levels of tumor-associated CD74 had significantly better outcomes in comparison with those with lower levels and high levels of IRF1 and PSME2 were also linked with better prognosis." (PMID 36226063, 2022). "These transcription factors are interferon regulator factors with tumor suppression effect in addition to activation of the innate immunity apoptosis and response to DNA damage for the factor irf1." (PMID 36517920, 2022). "Our data further support establishing IRF1 as a predictive biomarker in chemoradiotherapy in tumor patients." (PMID 35436994, 2022). "The IFN-γ/Stat1/IRF-1 axis plays an essential role in the communication between the tumor and the microenvironment." (PMID 36284313, 2022).
tumor (continued). "As a transcription factor that is involved in tumor-related signaling pathways, IRF-1 is often elevated in patients with ARDS." (PMID 35462787, 2022). "Among the 79 transcription factors, IRF1 was not only at the core in the gene interaction network but also enriched in the famous tumor pathway TNF, as detected by KEGG enrichment analysis." (PMID 36035205, 2022). "Interferon regulatory factor-1 (IRF-1) is an antiviral host factor that attenuates the replication of multiple RNA and DNA viruses and acts as a tumor suppressor." (PMID 35928153, 2022). "It has been reported that XAF1 interacts with IRF1 and inhibits IRF1 degradation during tumor therapy." (PMID 35972291, 2022). "IFN regulatory factor-1 (IRF-1), XIAP-associated factor 1 (XAF1), and cGMP-dependent protein kinase (PKG) II, as tumor suppressor genes, also can inhibit proliferation and promote apoptosis of GC in a similar way." (PMID 36505792, 2022). "IRF-1 can be recruited to the promoter of various genes to regulate immune responses, apoptosis, and tumor suppression." (PMID 35897807, 2022). "The IFN signaling pathway is known to be important in this process; for example, IRF1 acts as a tumor suppressor in a mouse model of CRC and in human cancer cells by promoting PANoptosis." (PMID 35205671, 2022). "This is in accordance with literature suggesting IRF1 as a biomarker for radioresistance in tumor cells." (PMID 35436994, 2022). "In line with previous studies, IRF1 expression was increased in tumours, displaying a proinflammatory immune phenotype upon EGFR inhibition." (PMID 36010935, 2022). "The induced expression of tumor suppressor IRF1 was found to alert antitumor immunity by activating immune effector cells and inhibiting cell proliferation of human cancer cells." (PMID 35664436, 2022). "When comparing the tumor growth of these IRF1 knockdown cells with immunotherapy, IRF1 knockdown reversed the observed combined effect of vitamin C treatment on tumor growth under immunotherapy." (PMID 35173532, 2022). "IRF1 determines tumor immunogenicity through induction of targets, such as antigen-presenting molecules (MHC class I, TAP, β2M) and ligands of immune inhibitory receptors (PD-L1 and PD-L2)." (PMID 36551603, 2022). "Consistent with our results in the database, GZMA, GZMB, IL18, and IRF1 were decreased in tumor tissues than normal tissues." (PMID 35464869, 2022). "Three tumor-associated antigens, CD74, IRF1, and PSME2, that showed overexpression, amplification, and mutation and were linked with prognosis and immune cell infiltration, were identified." (PMID 36226063, 2022). "Since IRF1 is responsible for regulating the expression of tumor suppressor genes (p73, FHIT, TGS101), these isoforms aggravate the proliferation and aggressiveness of this type of cancer." (PMID 35406498, 2022). "We used GEPIA for a pan-tumor analysis of IRF-1 expression, which showed that IRF-1 was differentially expressed in cancer tissues and its expression was inconsistent in different cancer tissues." (PMID 35092496, 2022). "Single cell RNA sequencing data confirm the existence of a tumor-infiltrating CXCL10+IRF1+STAT1+ M1-type TAM overexpressing antigen processing and presentation gene programs." (PMID 34220848, 2021). "Changes in IRF1 expression thus affect the dynamic balance between host anti-tumor immunity and tumor escape by regulating PD-L1 expression." (PMID 33476326, 2021). "Frequent loss-of-function mutations were also observed for CD58, IGLL5, IRF1, LTB, MGA and VMP1 in blood cancers, implicating a potential tumour-suppressive role of these genes in the pathogenesis in this tissue type." (PMID 33420369, 2021). "In OCs tissues, nuclear pSTAT1Y701 and IRF1 were detected in tumor cells and cells of the microenvironment." (PMID 34220848, 2021).
tumor (continued). "In the case of non-tumor cells, cellular sensors for transformation switch IRF1 actions from basal to active (during transformation events) or to inactive (when the insults have already been resolved)." (PMID 34589482, 2021). "Under the same study, an experiment on C57BL/6 mice with lycopene (40 mg/kg) administered intraperitoneally for 3 days resulted in the reduction of tumor volume, weight, IL-4, IL-10, gene expression of DMNT3a and methylation levels of promoters (IRF1, IRF7)." (PMID 34202203, 2021). "Interferon regulatory factor 1 (IRF1) is a tumor-suppressor gene that is associated with RCC, which can promote the apoptosis of tumor cells and increase tumor-cell sensitivity to chemotherapeutic drugs." (PMID 34445498, 2021). "Of note, STAT1+IRF1+ TAM have been observed in tumor-bearing mice with DICER conditional deletion and resulted in tumor inhibition by recruitment of activated CTL." (PMID 34220848, 2021). "By quantitative analysis, HiOC-IS30CD163Hi cases were significantly enriched of IRF1+ tumor cells (p = .0086) and pSTAT1Y701+ TAMs (p = .007) compared to LoOC-IS30CD163Lo." (PMID 34220848, 2021). "Regarding IRF1 activation, HEK293T and MDA-MB-231 cells showed considerably lower IRF1 activation than the non-tumor breast cells." (PMID 34589482, 2021). "Among other housekeeping activities exemplified by its role in tumor suppression, IRF1 protects the host from invading pathogens at multiple levels, ranging from an intrinsic ‘basal’ level to a robust ‘inducible’ function." (PMID 33476326, 2021). "With the exception of the MDA-MB-231 ER– cells, the transformed cells displayed similar nuclear levels of IRF1 to the non-tumor breast cells." (PMID 34589482, 2021). "TB11-Fhit-transfected tumor cells showed a significant increase in the expression of IRF-1, Jak1, Ptpsh1, Stat1, Stat2, and Stat3 genes." (PMID 32545680, 2020). "There are abundant high‐frequency mutations of proteins in the INF‐γ signaling pathway in tumor cells of immunocheckpoint‐resistant patients, such as IFN‐γ receptor 1 and 2, JAK1/2, and IRF‐1 (Interferon regulator factors 1)." (PMID 32875727, 2020). "Formation of the cellular complex between HPV16 E6 and IRF-1 plays an important role in regulating the anti-tumour and anti-angiogenic mechanisms." (PMID 33076322, 2020). "PSMB8, PSMB9, PSMB10, PSME2, TAP1, and IRF1 promote CD8+ T cell infiltration by enhancing MHC class I tumor antigen processing." (PMID 33330025, 2020). "Further evidence for this is that IRF1 expression in tumor cells is required for NK-mediated tumor lysis." (PMID 32499867, 2020). "Taken together, these results suggested that tumor cell-derived TNF-α promotes the expression of IL-33 in CAFs via the TNFR2/NF-κB/IRF-1 pathway." (PMID 31659258, 2020). "Our results show a novel mechanism by which entinostat initiates an IFIT1-STING-mediated potentiation of STAT4 via IRF1 to augment NK cell-mediated anti-tumor responses." (PMID 32499867, 2020). "Previous studies suggest that IRF-1 has an anti-tumor effect through growth inhibition and induction of apoptotic genes including caspase, tumor necrosis factor-related apoptosis-inducing ligand (TRAIL), and lysyl oxidase (LOX)." (PMID 32294904, 2020). "With regard to tumor suppressors, DSV–iECs showed an equal divide: 2 up-regulated (mutations: DNMT3A; CNAs: FANCA) and 2 down-regulated (CNAs: IRF1, BTG1) genes." (PMID 32934781, 2020). "IRF1 is known as an important regulator of genes involved in immune responses, inflammatory reactions, and tumor development." (PMID 32938919, 2020). "(c) HPV16 E6 directly binds with IRF-1 and regulates the cell cycle of HPV16 E6 by IRF-1 tumour suppressor." (PMID 33076322, 2020). "Luciferase activity was progressively diminished via transient transfection of tumour suppressor IRF-1 in a dose-dependent manner in CaSki cancer cells." (PMID 33076322, 2020).